ULK1 (unc-51 like autophagy activating kinase 1)
Diseases named in the same sentence as ULK1 in open-access papers (continued):
Sharing a sentence is not in itself a finding about the gene and the disease.
osteoporosis (6 papers, 2020 to 2024). A condition of reduced bone mass, with decreased cortical thickness and a decrease in the number and size of the trabeculae of cancellous bone (but normal chemical composition), resulting in increased fracture incidence. "The results showed that ULK1 expression was downregulated during osteoclast differentiation and was clinically associated with osteoporosis." (PMID 34820053, 2021). "Taken together, these results demonstrate that ULK1 activation confers resistance to bone destruction and oestrogen deficiency-induced osteoporosis." (PMID 34820053, 2021). "In vivo, ULK1 overexpression or a ULK1 agonist prevented bone loss in mouse osteoporosis models." (PMID 34820053, 2021). "Activation of ULK1 impeded bone loss in OVX mice with osteoporosis." (PMID 34820053, 2021). "Additionally, ULK1 expression in osteocytes decreases with age, which might contribute to the age-related bone loss in senile osteoporosis." (PMID 34820053, 2021). "In conclusion, our study has unveiled a potentially novel regulatory mechanism of OC differentiation mediated by the NDR2/ULK1/mitophagy axis, which has been validated in mice pathological models and osteoporosis patients." (PMID 39561008, 2024). "Meantime, we also found that Ampk does not appear to be responsible for phosphorylation of Acc since we observed significant increases in phosphorylation level of Ulk1 after irisin treatment in the senile osteoporosis mouse and the MLO-Y4 cells." (PMID 39559753, 2024). "In present study, we found that ULK1 expression was downregulated during OC differentiation, and downregulated ULK1 expression was correlated with osteoporosis." (PMID 34820053, 2021). "Ovariectomized (OVX) mouse model of osteoporosis and a mouse of model osteoclast-induced bone resorption were applied to explore the role of ULK1 in bone resorption in vivo." (PMID 34820053, 2021). "This study holds immense significance in further elucidating the role of kinase phosphorylation and ULK1-mediated autophagy in osteoporosis-related disorders, thereby offering potentially novel targets and a theoretical foundation for the prevention and treatment of bone metabolic diseases." (PMID 39561008, 2024). "As might be expected, irisin treatment increased phosphorylation of Ampk and of Ulk1 in the senile osteoporosis mouse model and in the MLO-Y4 cells." (PMID 39559753, 2024). "Our findings hold significant implications for further investigating the role of kinase phosphorylation and ULK1-mediated autophagy in osteoporosis-related diseases, while also offering targets and a theoretical foundation for preventing and treating bone metabolic disorders." (PMID 39561008, 2024). "Based on these findings, it is suggested that the NDR2/ULK1/mitophagy axis may play an important role in the occurrence and development of osteoporosis, providing insights for clinical prevention and treatment." (PMID 39561008, 2024). "Therefore, further research is needed to uncover the role of ULK1 in osteoclastogenesis and osteoporosis." (PMID 34820053, 2021). "Our study reveals a novel ULK1/DOK3/Syk axis that regulates OC differentiation, and targeting ULK1 is a potential therapeutic strategy for osteoporosis." (PMID 34820053, 2021). "Thus, activation of ULK1 may be a promising method for treating osteoporosis." (PMID 34820053, 2021). "Therefore, our study reveals a novel ULK1/DOK3/Syk axis that regulates osteoclast differentiation and bone resorption, and targeting ULK1 is a potential therapeutic strategy for osteoporosis." (PMID 34820053, 2021).
rheumatoid arthritis (6 papers, 2016 to 2025). A chronic, systemic autoimmune disorder characterized by inflammation in the synovial membranes and articular surfaces. "Additional variants of ULK1 have shown strong associations with tuberculosis and also with a specific type of rheumatoid arthritis termed ankylosing spondylitis, further linking ULK1 activity with the immune system." (PMID 33147747, 2020). "Oshtole can treat rheumatoid arthritis (RA) and suppress knee osteoarthritis (KOA) by enhancing autophagy activated by the AMPK/ULK1 pathway." (PMID 40563840, 2025).
Salmonella Infections (6 papers, 2018 to 2023). Infections with bacteria of the genus SALMONELLA. "In summary, this study demonstrated BCA induced AMPK/ULK1/mTOR-mediated autophagy and METs, which enhanced the defense against Salmonella infection in vitro and in vivo." (PMID 30271755, 2018). "Therefore, our study indicates that TAK1/AMPK/ULK1 plays a key role in LP postbiotic-activated autophagy to protect against Salmonella infection." (PMID 37893938, 2023). "A recent report showed that biochanin A improved defense against Salmonella infection both in vivo and in vitro by activating AMPK/ULK1/mTOR-mediated autophagy and macrophage extracellular traps (METs)." (PMID 35448466, 2022).
cervical cancer (5 papers, 2016 to 2023). A primary or metastatic malignant neoplasm involving the cervix. "RAME treatment increased the mRNA levels of ATG genes (ULK1, ATG5, BECN1, ATG7, ATG12, and ATG13) dose dependently in cervical cancer cells." (PMID 31387554, 2019).
Cognitive impairment (5 papers, 2023 to 2025). Abnormal cognition is characterized by deficits in thinking, reasoning, or remembering. "Similar findings have been reported in APP/PS1 mice, where autophagic activation in neurons and microglia alleviated amyloid pathology and cognitive impairment through the AMPK/mTOR/ULK1 pathway." (PMID 40589337, 2025). "ALT001 is a novel drug that ameliorates AD-related cognitive impairment via ULK1/Rab9-mediated alternative mitophagy." (PMID 40303347, 2025). "Mechanistically,NTRK1 knockdown might induce cognitive impairment and hippocampal neuron damage through the suppression of mitophagy via inactivating theAMPK/ULK1/FUNDC1 pathway." (PMID 37907480, 2023). "Resultantly, in vivo analysis revealed that NTRK1 knockdown induced mouse cognitive impairment and hippocampal tissue damage, in addition to inactivating the AMPK/ULK1/FUNDC1 pathway activity and mitophagy in the hippocampal tissues of mice." (PMID 37907480, 2023).
heart failure (5 papers, 2020 to 2025). Inability of the heart to pump blood at an adequate rate to meet tissue metabolic requirements. "Nevertheless, recent studies also indicated that gallic acid activates autophagy by inhibiting ULK1 phosphorylation, thereby suppresses cardiac hypertrophic remodelling and heart failure." (PMID 34632655, 2021).
liver cancer (5 papers, 2022 to 2025). An epithelial or non-epithelial malignant neoplasm that arises from the liver. "Western blotting verified that the combination treatment of Cabozantinib and IL-32γ overexpression significantly decreased the mTOR-related proteins (p-mTOR, p-4E-BP1, and p-S6 kinase) and MET but increased p-ULK1 in the liver cancer cell lines." (PMID 39519229, 2024). "According to a previous study, tan I activates the AMPK signaling pathway to active the ULK1 complex, which subsequently induces autophagy and prevents the growth of breast and liver cancer cells." (PMID 36172186, 2022). "Studies have shown that tan I inhibits the activity of mTORC1 under starvation conditions, subsequently increasing the activity of the ULK1 complex and promoting the occurrence of autophagy in breast and liver cancer cells." (PMID 36172186, 2022). "Unc-51 Like Autophagy Activating Kinase 1(ULK1) inhibitor can inhibit autophagy in liver cancer cells." (PMID 36278230, 2022). "In the present study, we found that MET was associated with mTOR analyzed by the STRING method with big database, and the IL-32γ overexpression reduced the mTOR and mTOR-related proteins (p-mTOR, p-4E-BP1, p-S6 kinase) expression but increased p-ULK1 in liver cancer cell lines." (PMID 39519229, 2024). "Furthermore, tan I activates the ULK1 complex and upregulates the expression level of Beclin 1, which subsequently induces autophagy and prevents the growth of breast and liver cancer cells." (PMID 36172186, 2022). "In addition, the combination treatment of Cabozantinib and IL-32γ overexpression further increased the expression of autophagy-related markers and p-ULK1; however, the expression levels of MET, p-mTOR, and mTOR-related proteins further decreased in liver cancer cell lines." (PMID 39519229, 2024).
lung adenocarcinoma (5 papers, 2020 to 2024). A carcinoma that arises from the lung and is characterized by the presence of malignant glandular epithelial cells. "In conclusion, this study discovered that chrysin suppresses autophagy activation in lung adenocarcinoma cells mediated by TAMs through the regulation of the CDK1/ULK1 pathway, which reverses the growth-promoting effect of TAMs on lung adenocarcinoma." (PMID 38675475, 2024). "Autophagy protects lung adenocarcinoma cells by decreasing ULK1 expression via the miR-106a-ULK1 axis." (PMID 38338839, 2024). "Copper is an essential regulator of the autophagic kinases ULK1/2 to drive lung adenocarcinoma." (PMID 38357312, 2024). "Furthermore, consistent with our previous study, it was observed that PLCγ1 inhibition blocked mTOR and ULK1 phosphorylation in lung adenocarcinoma A549 cells, suggesting thereby that the suppression of PLCγ1/mTOR/ULK1 axis might contribute to PLCγ1 inhibition-driven autophagy." (PMID 32210730, 2020).
oral cancer (5 papers, 2021 to 2024). "Otherwise, ULK1 can regulate autophagy in oral cancer and can be used as a new potential target to evaluate the prognosis of oral cancer and improve chemotherapeutic effect." (PMID 35692501, 2022). "To better explore the function of miR-214 in oral cancer progression and its correlation with ULK1, as well as the effect of autophagy on chemotherapy, we carried out experiments in CAL-27 cells." (PMID 35692501, 2022). "The increased acetylation of ULK1 results in the activation of autophagy in the SAS oral cancer cell line." (PMID 34585646, 2021). "Moreover, to further determine the impacts of miR-214 and ULK1 on oral cancer cell growth after chemotherapy, the two were overexpressed or silenced in CAL-27 cells after transfection." (PMID 35692501, 2022). "Therefore, to study the correlation between miR-214 and ULK1 mediated autophagy and to explore their effects on tumor cell proliferation after chemotherapy is of great implications for oral cancer diagnosis and therapy." (PMID 35692501, 2022). "Hence, this research is aimed at determining miR-214 and ULK1 expression in oral cancer before and after chemotherapy and their correlations with cancer cell growth." (PMID 35692501, 2022). "Therefore, miR-214 can be used as an early prognostic biomarker for oral cancer, and ULK1 is a new candidate therapeutic target." (PMID 35692501, 2022). "Therefore, for oral cancer, miR-214 can be an early prognostic biomarker while ULK1 is a new candidate therapeutic target." (PMID 35692501, 2022). "However, one study showed that capsaicin inhibits SIRT1 to enhance the acetylation of unc-51-like autophagy activating kinase 1 (ULK1) to trigger autophagy in oral cancer cells, which suggests that SIRT1 may inhibit autophagy in oral cancer cells." (PMID 36815979, 2023). "As expected, the level of HIF-1α, Lon, ULK1, and ULK1 downstream autophagy proteins, ULK1-S555 phosphorylation, ATG13, and FIP200, was increased under hypoxia exposure or CoCl2 treatment in HCT-15 colorectal cancer cells and in FADU, HSC-3 and OEC-M1 oral cancer cells." (PMID 36927870, 2023). "We found that the initiation proteins of autophagy were increased and ULK1 downstream target proteins were significantly activated upon Lon overexpression whereas the initiation proteins of autophagy were inhibited in the Lon-shRNA HCT-15 cells and in OEC-M1 oral cancer cells." (PMID 36927870, 2023). "However, there has been no study on miR-214/ULK1 axis in oral cancer." (PMID 35692501, 2022).
tuberculosis (5 papers, 2020 to 2025). A chronic, recurrent infection caused by the bacterium Mycobacterium tuberculosis. "In addition, in mycobacterium tuberculosis-induced infection, LncRNA MIAT regulated autophagy and apoptosis of macrophages through the miR-665/ULK1 signaling axis." (PMID 37175724, 2023).
amyotrophic lateral sclerosis (4 papers, 2017 to 2025). Amyotrophic lateral sclerosis (ALS) is a neurodegenerative disease characterized by progressive muscular paralysis reflecting degeneration of motor neurons in the primary motor cortex, corticospinal tracts, brainstem and spinal cord. "Furthermore, C9orf72 (chromosome 9 ORF 72) a protein mutated in the neurodegenerative disorder ALS (amyotrophic lateral sclerosis), has recently been reported to regulate the ULK1 complex." (PMID 29233870, 2017). "Heet al. verified that the ULK1 activator BL-918 has therapeutic potential for amyotrophic lateral sclerosis through the induction of cytoprotective autophagy." (PMID 39175431, 2024).
atherosclerosis (4 papers, 2017 to 2025). A disease characterized by the build-up of fatty material and calcium deposition in the arterial wall resulting in partial or complete occlusion of the arterial lumen. "Studies had shown that GPS (2.973 g/kg for 4 weeks, i.g.)might enhance the level of autophagy of AS model mice by regulating the mTOR/unc-51-like kinase 1 (ULK1) autophagy signaling pathway, alleviate the formation of atherosclerotic plaque, and prevent atherosclerosis." (PMID 34684830, 2021). "In summary, this study demonstrated that moderate autophagy induced by low-dose rapamycin could alleviate atherosclerosis progression and promote plaque stability in the ApoE−/− mice model, which was associated with regulating VSMC autophagy and senescence by the mTORC1/ULK1/ATG13 signal pathway." (PMID 28713484, 2017).
cardiomyopathy (4 papers, 2020 to 2025). A disease of the heart muscle or myocardium proper. "Mitophagy also plays a crucial role in preventing diabetes-induced cardiomyopathy, particularly for ULK1/Rab9 (Ras-related protein 9)-mediated mitophagy." (PMID 36312227, 2022). "The accumulation of mitochondrial ROS is involved in the progression of DOX cardiomyopathy via the regulation of UNC-51-like kinase 1 (ULK1) phosphorylation at multiple binding sites." (PMID 33143122, 2020). "In a model of doxorubicin‐induced cardiomyopathy and fibrosis, activating the AMPK/ULK1/FUNDC1 pathway reduces ROS levels, improves mitochondrial membrane potential, and increases mitophagy, thereby ameliorating cardiomyopathy." (PMID 40535916, 2025).
esophageal cancer (4 papers, 2021 to 2024). A primary or metastatic malignant neoplasm involving the esophagus. "We also knocked down ULK1 expression in esophageal cancer cells and showed that the effect of CUDC-907-induced autophagy was weakened." (PMID 35989326, 2022). "Based on these observations, we concluded that CPT-induced ROS production modulated the AMPK/mTOR/ULK1 pathway to induce autophagy in esophageal cancer cells." (PMID 33898327, 2021). "In our study, we elucidate a novel mechanism of the NF-κB/AMPK/mTOR/ULK1 pathway in CPT-induced protective autophagy in esophageal cancer cells, which provides a sound rationale for combinational anti-ESCC therapy with CPT and inhibition AMPK/ULK1 pathway." (PMID 33898327, 2021). "Therefore, we further used western blotting to confirm that SJC activated autophagy in esophageal cancer cells through the AMPK/ULK1 signaling pathway." (PMID 36120378, 2022). "Therefore, we speculate that SJC promotes autophagy in esophageal cancer cells through the AMPK/ULK1 signaling pathway." (PMID 36120378, 2022). "Recently, research also shows that Salvia chinensia Benth treat esophageal cancer cells which resulted in the upregulation of p-AMPK and p-ULK1 expression, activation of signaling pathways, and increased accumulation of autophagy marker LC3." (PMID 39502521, 2024).
ischemia (4 papers, 2020 to 2025). A hypoperfusion of the BLOOD through an organ or tissue caused by a PATHOLOGIC CONSTRICTION or obstruction of its BLOOD VESSELS, or an absence of BLOOD CIRCULATION. "Together, these results suggest that the modulating effects of AMPK/mTOR/ULK1 signaling on endogenous autophagy were weakened on day 3 after ischemia, whereas DADLE-mediated DOR activation augmented autophagy by triggering AMPK/mTOR/ULK1 signaling." (PMID 32549974, 2020). "DADLE-evoked DOR activation enhanced neuronal autophagy through activating the AMPK/mTOR/ULK1 signaling pathway to improve neuronal survival and exert neuroprotective effects against ischemia." (PMID 32549974, 2020). "For example, Ulk1/Rab9 mediated alternative autophagy could prevent mouse hearts from ischemia injuries." (PMID 35361231, 2022). "These in vivo results indicate that the effect of DADLE against ischemia could be attributed to a DOR/AMPK/mTOR/ULK1 signaling pathway-dependent increase in autophagic activity." (PMID 32549974, 2020). "The decreased p-AMPKα T172 level and elevated level of p-ULK1 S317 implies that the modulatory effects of AMPK signaling were exhausted, while ischemia-induced autophagy continued until the 3rd day after ischemia." (PMID 32549974, 2020).
lymph node metastasis (4 papers, 2016 to 2024). "Nevertheless, in our study, increased ULK1 expression was significantly associated with the presence of lymph node metastasis." (PMID 27444698, 2016). "ULK1 positive staining was significantly associated with the presence of lymph node metastasis (p = 0.037, chi-square analysis)." (PMID 27444698, 2016). "In our experiment, we analyzed correlation between the expression pattern of Beclin1, ULK1, bcl2 and LC3 with clinical and pathological features (subtype, stage, lymph node metastasis and smoking)." (PMID 33773561, 2021).
myeloma (4 papers, 2018 to 2025). "In our study, TEM observations showed accumulation of autophagosomes in metformin-treated myeloma cells and expression of the Atg1/ULK1 complex, the downstream target of mTORC1 and the central regulator of autophagy, was found to be simultaneously elevated." (PMID 29554968, 2018). "We demonstrated miR-25 mediates Dex resistance in myeloma via targeting ULK1 and p27." (PMID 34983615, 2022). "For instance, in the CD4+ T cells in samples from patients with myeloma or AL amyloidosis, six analytes (phospho‐p38 MAPK, phospho‐RIP, phospho‐Shp2, phospho‐SQST, phospho‐STING, and phospho‐ULK1) demonstrated high levels of bivariate correlations." (PMID 40977494, 2025). "The mononuclear cells from AL amyloidosis patients had lower expression levels than the cells from myeloma patients for BDNF, calmodulin, phospho‐TBK1, and phospho‐ULK1 in CD4+ T cells and phospho‐GSK3β in monocytes, but higher levels of HO1 in monocytes." (PMID 40977494, 2025).
nasopharyngeal carcinoma (4 papers, 2019 to 2025). A carcinoma arising from the nasopharyngeal epithelium. "Their findings revealed a strong correlation between elevated ULK1 levels and aggressive clinical features, as well as poor survival rates in individuals with nasopharyngeal carcinoma." (PMID 39664581, 2024). "The role of Unc-51-Like Autophagy Activating Kinase 1 (ULK1/ATG1) in the regulation of autophagy presents a critical area of investigation, particularly in the context of nasopharyngeal carcinoma (NPC)." (PMID 40630202, 2025).